ST8SIA4 (ST8 alpha-N-acetyl-neuraminide alpha-2,8-sialyltransferase 4)
Diseases named in the same sentence as ST8SIA4 in open-access papers (continued):
Sharing a sentence is not in itself a finding about the gene and the disease.
tumor (11 papers, 2016 to 2025). "This association suggests that St8sia4 plays a pivotal role in altering the tumor microenvironment, thereby facilitating tumor growth and metastasis." (PMID 39131703, 2024). "The protein levels of PI3K p110α, p-Akt T380, p-Akt S473, p-mTOR and ST8SIA4 were decreased in the xenograft tumour tissues transfected with miR-146a/b antagomirs (*p < 0.05)." (PMID 28427206, 2017). "A significant decrease in tumour weight was observed in ST8SIA4-overexpressing tumours, and tumour weights were increased in the ST8SIA4-inhibited tumours compared with those of the controls (*p < 0.05)." (PMID 28427206, 2017). "In addition, a lasso regression analysis revealed that the expression of ST8SIA4 and other glycosylation factors is positively correlated with pro-tumoral M2 macrophages in various tumor types." (PMID 36009354, 2022). "IHC staining also showed the reduced protein levels of ST8SIA4 and Ki67 in the tumor tissues." (PMID 28032858, 2016). "We further assessed whether ectopic expression of ST8SIA4 inhibited tumour growth in vivo." (PMID 28427206, 2017). "Studies correlating the ST8SIA family with tumor progression are mainly related to ST8SIA1 and ST8SIA4." (PMID 33921986, 2021). "Inhibiting polysialyltransferases ST8SIA2 and ST8SIA4 decreased polysialylation of NCAM, resulting in delayed metastasis in a xenograft rhabdomyosarcoma tumor mouse model." (PMID 31979120, 2020). "Through in silico analysis we showed that mRNAs of only ST6GAL1, ST3GAL2 and ST8SIA4 are significantly upregulated in GBM tissues compared to non-tumor ones." (PMID 41226744, 2025). "Similarly, ST8SIA4 knockdown inhibited MDA-MB-231 cell proliferation in vitro and tumor development in vivo, as seen by the decrease in Ki67-positive cells in the tumor tissue." (PMID 36547200, 2022). "ST8SIA4, B4GALT5, and CSGALNACT2 were found to be downregulated in Fra-2 cl 2 scid primary tumours." (PMID 34693476, 2022). "Likewise, knockdown of ST8SIA4 repressed MDA-MB-231 cell proliferation in vitro and tumor growth in vivo, as demonstrated by the reduction of Ki67-positive cells in the tumor tissue." (PMID 33921986, 2021). "Based on the significant alterations in ST8SIA4 and ST8SIA6 expression in the highly invasive FTC cells, we investigated whether these two ST8SIA members could affect the tumour properties of FTC cells." (PMID 28427206, 2017). "Importantly, the FTC-133 cells transfected with the ST8SIA4 expression vector reversed the tumour growth induced by miR-146a/b in vivo, whereas the FTC-238 cells transfected with the ST8SIA4-specific shRNA reversed the tumour growth inhibitory effect of miR-146a/b inhibition in vivo." (PMID 28427206, 2017).
infection (2 papers, 2020 to 2023). The state of being infected such as from the introduction of a foreign agent such as serum, vaccine, antigenic substance or organism. "We observed that these genes did not change expression in non-CF ALI cultures upon infection with RV; ST8SIA4 (3.6-fold, p = 0.14); ST6GALNAC2 (−1.3-fold, p = 0.09); MAN1A1 (5.4-fold; p = 0.08); B3GNT8 (1-fold, p = 0.28)." (PMID 32765492, 2020).
immune dysfunctions (1 paper, 2020). "The polysialyltransferase ST8SIA4 has been identified in a multiplex meta-analysis of RNA expression datasets as one of the top deregulated genes associated with various immune dysfunctions." (PMID 32603365, 2020).
ST8SIA4 also shares sentences with these, for which no sentence is quoted: acute myeloid leukemia (1 paper); Brugada syndrome (1); Cognitive impairment (1); neuroblastoma (1); ovarian carcinoma (1); prostate carcinoma (1); typhoid (1).